FGF23 (fibroblast growth factor 23)
Diseases named in the same sentence as FGF23 in open-access papers (continued):
Sharing a sentence is not in itself a finding about the gene and the disease.
testicular tumor (1 paper, 2025). "Production and release of FGF23 in GCNIS and EC cells were examined by measuring the total FGF23 (iFGF23+cFGF23) and cFGF23 concentrations in seminal fluid from healthy men and testicular tumor patients." (PMID 40279260, 2025).
thymic atrophy (1 paper, 2019). "Parathyroid hormone (PTH) and fibroblast growth factor 23 (FGF23), which are mineral and bone disorder (MBD)-related factors, affect immune cells and possibly cause thymic atrophy." (PMID 30692566, 2019). "Although neither serum level of FGF23 nor phosphorus were found to be associated with thymic atrophy in the present study, there is a possibility that it was not related to phosphorus metabolism because of the differences between humans and mice." (PMID 30692566, 2019). "This study showed that thymic atrophy was associated with higher PTH level, but not with FGF23 or ALP level, after adjustment for eGFR, active vitamin D supplementation, and other variables." (PMID 30692566, 2019).
thyroid cancer (1 paper, 2020). "Elevation of FGF23 levels have been shown to be a surrogate marker of FGFR1 inhibition, and in particular, circulating FGF23 levels were increased by Lenvatinib therapy in thyroid cancer." (PMID 31991869, 2020).
transport (1 paper, 2022). "In addition, FGF23 is involved in regulating the activity of renal enzymes and reducing the activity of specific transporters, resulting in sodium—phosphate co-transport disorder and electrolyte metabolism imbalance." (PMID 35546659, 2022).
cardiovascular disease (198 papers, 2010 to 2026). "Elevated FGF23 is positively associated with the risk of cardiovascular diseases in the general population and patients with CKD including those on hemodialysis (HD)." (PMID 39807363, 2025). "Conversely, our prior cross-sectional study demonstrated that low FGF-23 is associated with the presence of cardiovascular diseases." (PMID 40136613, 2025). "Elevated FGF-23 levels have also been linked to a higher risk of cardiovascular events or all-cause mortality in patients with cardiovascular disease." (PMID 39989455, 2025). "The combination of elevated FGF23 and Klotho deficiency contributes to cardiovascular diseases in patients with CKD." (PMID 38792509, 2024). "Increased fibroblast growth factor 23 (FGF23)—the earliest detectable serum abnormality associated with CKD-MBD—has been linked with cardiovascular disease in patients with CKD." (PMID 39433982, 2024). "Previous studies have shown that elevated serum levels of FGF23 are associated with an increased risk of cardiovascular disease, including CI." (PMID 39096857, 2024). "FGF23 also induced oxidative stress and endothelial cell dysfunction, potentially contributing to the progression of cardiovascular diseases in states of Klotho deficiency." (PMID 38846254, 2024). "In patients undergoing incident hemodialysis, increased fibroblast growth factor-23 (FGF-23) levels are associated with the development of cardiovascular disease (CVD), but the influence of residual kidney function (RFK) on this association is unclear." (PMID 37501787, 2023). "Associations of serum intact FGF-23 with cardiovascular diseases and the interaction of intact FGF-23 with residual kidney function." (PMID 37501787, 2023). "Conventionally observed associations between FGF-23 with cardiovascular disease are likely due to residual confounding." (PMID 36719157, 2023). "High FGF23 availability is associated with declined metabolic function and cardiovascular disorders." (PMID 36831188, 2023). "FGF23 has been associated with the disturbance of mineral homeostasis, and with kidney and cardiovascular diseases." (PMID 37627287, 2023). "Due to the potential of T2 to induce 1,25(OH)2D degradation, activate VDR, and increase FGF23, which is associated with cardiovascular diseases, the safety of UV-B-treated foods is questionable." (PMID 35958252, 2022). "The last biomarker independently associated with MACE in our cohort was FGF-23, a phosphorus regulating protein secreted by osteoblasts and a recently described risk factor for cardiovascular disease." (PMID 35211520, 2022). "FGF23 is involved in inflammatory reactions closely associated with an incremented risk of cardiovascular disease (CVD)." (PMID 36498673, 2022). "Elevated levels of testosterone and fibroblast growth factor 23 (FGF-23) are both independently associated with a higher risk of cardiovascular disease (CVD)." (PMID 35613118, 2022). "Recent studies indicate that elevated FGF23 concentrations are linked to cardiovascular disease, and are therefore correlated with mortality in CKD patients." (PMID 33606750, 2021). "While a previous observational study including 32 RRMS patients found overexpression of FGF23 in MS patients (p < 0.01) and an association of high FGF23 levels (approximately 2.5-fold higher) with comorbidities such as cardiovascular diseases in MS." (PMID 34745143, 2021). "The elevated serum concentrations of sP and FGF23 are associated with cardiovascular disease and increased mortality in human patients with CKD." (PMID 33606750, 2021). "Klotho and FGF-23 have been already associated with cardiovascular disease mortality in patients with CKD." (PMID 33160321, 2020). "In recent years, high FGF-23 plasma levels have been shown to be associated with cardiovascular disease and incidence of mortality and cardiovascular events." (PMID 32967202, 2020).
cardiovascular disease (continued). "Fibroblast growth factor 23 (FGF23), which is involved in the regulation of vitamin D, is an emerging independent risk factor for cardiovascular diseases." (PMID 33424930, 2020). "Increased FGF23 levels have cross-sectionally been associated with vascular risk factors, including smoking, waist circumference, history of cardiovascular disease and serum glucose levels." (PMID 30830941, 2019). "Some of these diseases, particularly renal and cardiovascular diseases, are associated with elevated FGF23 plasma levels, and FGF23 not only indicates disease, but actively contributes at least to left heart hypertrophy." (PMID 30921339, 2019). "A matter of concern for clinicians is that high levels of FGF23 are strongly associated with cardiovascular disease (CVD), and an independent predictor of mortality." (PMID 30086150, 2018). "Specifically, recent epidemiological studies have linked a high plasma level of the phosphaturic hormone fibroblast growth factor 23 (FGF23) with an increased risk of cardiovascular disease in CKD patients." (PMID 29137111, 2017). "Higher levels of FGF23 have been reported to be associated with cardiovascular disease such as LV hypertrophy in both human and experimental studies." (PMID 27579618, 2016). "In this study, we predominantly focus on the associations of baseline FGF23 serum concentration and subsequent changes in markers of kidney and cardiovascular disease." (PMID 27176000, 2016). "The influence of a first-degree FHD on serum FGF23 levels should be considered to avoid overestimating the risk of cardiovascular disease in normoglycemic individuals with a first-degree FHD." (PMID 27698482, 2016). "Higher FGF23 has emerged as a risk factor for progressive decline in kidney function and increased cardiovascular disease (CVD) event rates." (PMID 25811862, 2015). "Prospective studies are warranted to ascertain the potential pathogenic role of FGF-23 and vitamin D in the development of AS and cardiovascular disease in patients with T1DM." (PMID 26462160, 2015). "FGF-23 has been revealed as a potential useful biomarker not only for cardiovascular disease in high-risk populations, such as CDK patients, but even in the general population." (PMID 26462160, 2015). "Previously, a positive association between recurrent cardiovascular disease and high FGF23 levels was reported in The Heart Soul Study." (PMID 26459301, 2015). "Recent translational reports have described the existence of FGF23-Klotho axis in the vasculature and the causative effect of FGF23 on cardiovascular disease." (PMID 24678415, 2014). "Increasing levels of FGF23 are associated with increased cardiovascular disease and mortality in the community." (PMID 25166750, 2014). "This should be put in the context that abnormally high levels of FGF23 in humans are associated with adverse clinical outcomes including cardiovascular disease, CKD progression rate and mortality." (PMID 24348262, 2013). "For some factors, like GFR[1???] and phosphate level, both reasonably established novel risk factors for cardiovascular disease, its relationship with FGF23 is well described." (PMID 22530966, 2012). "In the current study we investigated the association of FGF23 with established cardiovascular risk factors, and with additional specific renal risk factors for cardiovascular disease in a large well-described cohort of patients with moderate to severe CKD." (PMID 22530966, 2012). "Thus, decreased FGF23 levels due to the normalized calcium and phosphorus balance after parathyroidectomy are associated with decreased risk of cardiovascular disease." (PMID 38530609, 2024). "However, the role of FGF23 in stress pathways has been largely overlooked, although it is known to be associated with inflammation, renal and cardiovascular disease, and proinflammatory pathways." (PMID 39329699, 2024).
cardiovascular disease (continued). "In this group of patients, different mechanisms may contribute to an increased risk of cardiovascular diseases in women in later life, and FGF23 appears to be their promising early predictor." (PMID 38139126, 2023). "In this group of patients, different mechanisms may contribute to an increased risk of cardiovascular disease in later life, and FGF23 appears to be a promising early predictor of these complications." (PMID 38139126, 2023). "In a meta-analysis on FGF-23 and risks of cardiovascular and non-cardiovascular diseases the authors concluded that the association between FGF-23 and the diseases might be non-causal." (PMID 37600039, 2023). "However, elevated levels of FGF-23 are associated with a higher incidence of cardiovascular disease (CVD) and mortality among CKD patients." (PMID 35613118, 2022). "Increased FGF23 levels have been linked to cardiovascular disease and mortality." (PMID 35231062, 2022). "A still unresolved question in this respect is whether FGF23 is just a good biomarker or whether there is a causal link between FGF23 and cardiovascular disease." (PMID 34290280, 2021). "In CKD patients, FGF23 is associated with impaired endothelial-dependent relaxation, endothelial-independent relaxation, arterial stiffness and cardiovascular disease; however, the effects of FGF23 in the acute setting are largely unknown." (PMID 30971270, 2019). "A number of epidemiological studies in humans have reported associations between increased circulating FGF23 concentrations and vascular dysfunction, vascular calcification and increased risk of cardiovascular disease." (PMID 31372314, 2019). "The fact that FGF23 may cause undesirable effects raises the question of whether it may not only be a biomarker of altered mineral metabolism and cardiovascular disease, but a therapeutic target." (PMID 30909513, 2019). "In CKD, elevated FGF-23 initially functions to maintain mineral homeostasis, but persistent elevations are maladaptive and associated with increased morbidity and mortality, cardiovascular disease, inflammation, and infections." (PMID 29946298, 2018). "Thus, it is important to characterize this interrelationship since all of the three components, phosphate, inflammation, and FGF23 appear to be independently associated with mortality and cardiovascular disease in dialysis patients." (PMID 30086150, 2018). "It is not clear, however, whether increased circulating FGF23 levels in patients with CKD are causative of cardiovascular disease, or whether FGF23 is simply a biomarker for CKD-MBD severity." (PMID 24885942, 2014). "If FGF23 indeed has a causative role in cardiovascular disease and is involved in progression of CKD, an important next step would be to test the hypothesis that dietary or pharmacological interventions aimed at a reduction of FGF23 improves these outcomes." (PMID 22530966, 2012). "Indeed, some authors suggest that FGF23 may be a consequence rather a cause of cardiovascular disease, since patients from the general population may show a comparable risk of death to that of dialysis patients, suggesting casualty rather than causality." (PMID 30909513, 2019). "Furthermore, many patients in the control group had CHD, which could have influenced our results because FGF23 is a known risk factor for cardiovascular disease." (PMID 30236113, 2018). "Increased FGF23 levels, in patients with cardiovascular disease, were a predictor of cardiac events and have been associated with left ventricular hypertrophy and prevalent cardiovascular disease in elderly individuals with normal renal function in the population studied." (PMID 26459301, 2015). "FGF23, a key regulator of mineral metabolism, increases in CKD and has been associated with cardiovascular disease." (PMID 41152128, 2025). "Crucially, abnormal levels and activity of Klotho and FGF23 are highly related to cardiovascular disease (CVD)." (PMID 41574188, 2025).
cardiovascular disease (continued). "Dysregulated mineral metabolism in CKD is closely linked to iron dyshomeostasis and contributes to adverse patient outcomes, including bone diseases and cardiovascular disease, in part through greatly increased FGF23 levels." (PMID 40773297, 2025). "Cardiovascular disease OR heart disease ("cardiovascular diseases/blood"[Mesh] OR "cardiovascular diseases/diagnosis"[Mesh] OR "cardiovascular diseases/etiology"[Mesh]) AND FGF23 OR fibroblast growth factor 23 OR fibroblast growth factor-23/blood"[Majr]." (PMID 38846254, 2024). "The high level of FGF23 in serum negatively regulates the synthesis of 1,25-dihydroxyvitamin D [1,25 (OH) D], triggering cardiovascular diseases, weakness, disability, and other adverse consequences." (PMID 38509497, 2024). "One of the most important reasons for the increased risk of cardiovascular disease and mortality in CKD patients is elevated fibroblast growth factor 23 (FGF23) and phosphate levels." (PMID 38530609, 2024). "The fact that FGF23 was related both to disease damage and, albeit univariably, cIMT would support a relationship between FGF23 and cardiovascular disease in patients with SLE." (PMID 37627287, 2023). "The increased expression of Fgf23 mRNA in osteocytes derived from Herc1-KO mice suggests an association between HERC1 loss-of-function and renal and cardiovascular disease." (PMID 36635269, 2023). "We also found that the association between a high FGF-23 level and RKFD was more significant in the subjects with cardiovascular disease." (PMID 36671416, 2022). "Plasma FGF23 concentration early rises in kidney and cardiovascular diseases correlating with progression and outcome." (PMID 34731356, 2022). "Third, elevations in parathyroid hormone (PTH), which together with FGF23 keep serum concentrations of phosphate under tight control, have also been related to the development of cardiovascular disease." (PMID 36221075, 2022). "Recently, studies have shown that FGF-23 has a regulatory role in the pathological process of various cardiovascular diseases, and it has the potential to become a clinical biomarker for predicting the risk of MACCE." (PMID 36132198, 2022). "The role of FGF23 in CKD and the associated cardiovascular disease has been the subject of many studies over the last decade." (PMID 36699036, 2022). "We previously showed in Col4a3KO mice with CKD that overexpression of a bone matrix protein, DMP1, or treatment with ferric citrate, an iron-based phosphate binder, reduces FGF23 production and cardiovascular disease." (PMID 34334787, 2021). "All these studies point to FGF-23 as an important and independent biomarker involved in several pathologic processes, including cardiovascular disease." (PMID 33767635, 2021). "Discussions of SHPTH need to consider fibroblast growth factor-23 (FGF23) and klotho to form accurate assessments of links to important outcomes such as cardiovascular disease." (PMID 33022030, 2021). "Existing evidence shows that there is a clear correlation between FGF23 and the occurrence of vascular calcification and cardiovascular disease (CVD)." (PMID 34367315, 2021). "The relationship between increased systemic FGF-23 levels and vascular calcification has been shown experimentally in in vitro approaches, in patients with established cardiovascular disease, in pre-dialysis diabetic and in CKD patients." (PMID 33767635, 2021). "Recently, several clinical studies suggest that FGF-23, as a pro-inflammatory role, is involved in several aspects of cardiovascular diseases." (PMID 33413149, 2021). "In this review, we identify the agreements and contradictions between clinical studies and put forward a scenario in which the specific role of FGF-23 in cardiovascular diseases can also be significantly harmful." (PMID 33767635, 2021). "Recently, increasing evidence has indicated a strong relationship between FGF23 and cardiovascular diseases." (PMID 33424930, 2020).